ENSG00000199927
Gene: Small nucleolar RNA gene on chromosome 3 (30,304,320 to 30,304,536, reverse strand). Ensembl gene ENSG00000199927.
Gene Ontology:
Biological process: RNA processing
Cellular component: nucleolus
Homologues: Orthologues: mouse Gm24826 (79% identical), mouse Snord3b-ps1 (79% identical), mouse Gm25203 (78% identical). Paralogues in human: SNORD3D (81% identical).